KRAS (KRas proto-oncogene, GTPase)
Diseases named in the same sentence as KRAS in open-access papers (continued):
Sharing a sentence is not in itself a finding about the gene and the disease.
pancreatic cancer (continued). "Using the KC mouse model, a model where KRAS genetic changes are brought in for the development of pancreatic cancer, the immune cell infiltration at different stages of PDAC, including normal pancreas, PanINs, and invasive carcinoma, were examined." (PMID 38384463, 2024). "KRAS is mutated in the majority of pancreatic adenocarcinoma cases, and researchers recently showed that targeting KRAS in treatment of pancreatic cancer produced promising results." (PMID 39410042, 2024). "Pancreatic cancer's resistance to conventional treatment is partly due to the reprogramming of multiple metabolic pathways by the mutant KRAS gene." (PMID 39609317, 2024). "Activating mutation of KRAS in pancreatic cancer cells AsPC-1 leads to hyperphosphorylation of ERK1/2 kinase, causing proliferation and growth of pancreatic cancer cells." (PMID 38448410, 2024). "Studies involving the suppression of RAGE expression, either through knockdown or knockout approaches, have demonstrated a notable delay in the growth of pancreatic tumors driven by oncogenic KRAS." (PMID 39087024, 2024). "Pearson correlation was conducted between EPLIN and some key players in KRAS-activated signalling events in the pancreatic cancer TCGA database." (PMID 39730634, 2024). "While there are many promising KRAS inhibitors in preclinical and clinical development, we focus on reviewing those that we think are most relevant for patients with pancreatic cancer." (PMID 38800401, 2024). "The PROTAC down-regulation of AKT proteins markedly slowed the growth of three pancreatic tumor cell lines harboring mutant KRAS." (PMID 38920688, 2024). "In summary, our findings highlight the discernible changes in metabolite profiles induced by TRPML1 inhibition using ML-SI1, offering insights into the diverse metabolic pathways affecting KRAS-mutant pancreatic cancer cells." (PMID 38672219, 2024). "Key Ras-driven cancers include pancreatic cancer and non-small cell lung cancer (NSCLC), both of which are primarily caused by mutations in KRAS." (PMID 39372214, 2024). "Both AMG-510 and BI-3406 significantly reduced colony formation and anchorage independent growth of KRAS G12C mutant MiaPaCa pancreatic cancer cells." (PMID 38892436, 2024). "Western blotting evaluated the p-EGFR/KRAS/p-ERK1/2 signaling pathway in pancreatic cancer cells (PANC-1 and MIA PACA-2) under individual and combined CSI and erlotinib treatments." (PMID 39770538, 2024). "The evidence of safety and efficacy from clinical trials supports the feasibility of selectively targeting FTH1 in cancer therapy, opening up new avenues for treatment strategies for KRAS-mutant pancreatic cancer." (PMID 39294443, 2024). "KRAS is widely known as the critical driver that enables unlimited proliferation, apoptosis resistance, and metastasis in pancreatic cancer cells and promotes metabolic alterations for the sustenance of biosynthetic pathways." (PMID 39294443, 2024). "Pancreatic ductal adenocarcinoma (PDAC) is the most common type of pancreatic cancer, and nearly 95% of patients with PDAC harbor a KRAS mutation." (PMID 39294443, 2024). "Increased Ral activity has also been shown in KRAS-4B G12V-mutant pancreatic cancer, due to altered binding kinetics and a more dynamic interaction between KRAS-4B G12V and the RalGEF Rgl2, compared to the KRAS WT interaction with Rgl2." (PMID 39372214, 2024). "Targeting mTOR signaling to prevent adaptive resistance to KRAS inhibitors has also been reported for non-small cell lung cancer and pancreatic cancer models." (PMID 38992135, 2024).
pancreatic cancer (continued). "Presently, there are two ongoing clinical trials investigating the efficacy of KRAS-targeted SLP vaccines in pancreatic cancer treatment." (PMID 39329989, 2024). "Considering the function of STAT3–ZDHHC20 axis in KRAS mutant pancreatic cancer above, we explore the biological effect of these proteins in the CDX model." (PMID 38821916, 2024). "Lastly, and perhaps most importantly, our findings also apply to resistance against KRAS G12D inhibition in pancreatic cancer cells." (PMID 39704172, 2024). "Other siRNAs have been designed to specifically target KRAS G12D, such as siG12D-LODER, which is in clinical trials against KRAS G12D-driven pancreatic cancer." (PMID 38668053, 2024). "ZC3HAV1, a PARP family enzyme, promotes proliferation and metastasis by regulating KRAS in pancreatic cancer and is involved in facilitating DNA repair and promoting tumorigenesis in breast cancer." (PMID 38745208, 2024). "Silencing mutant KRAS in human pancreatic cancer cells using specific siRNA effectively reduces KRAS expression, leading to a dose-dependent decrease in KRAS protein levels." (PMID 38666907, 2024). "In this study, we elucidated new mechanistic pathways highlighting the interplay between FTH1 and PYCR1, which appears to form a self-reinforcing loop that collectively drives the progression of KRAS-mutant pancreatic cancer." (PMID 39294443, 2024). "The second highest co-occurring pair in the common gene projection, CDKN2A and KRAS, also majorly occurs in pancreatic cancer." (PMID 39040139, 2024). "The results of RT‒qPCR and western blot analyses showed that KRAS G12D inhibitor treatment significantly downregulated ZDHHC20 expression in pancreatic cancer cells." (PMID 38821916, 2024). "Primers were designed for hotspot regions in the KRAS (codon 12 and 13) and GNAS (codon 201) genes to detect well-characterized driver mutations in pancreatic cancer by Sanger sequencing." (PMID 38472986, 2024). "We investigated the cancerous features of pancreatic cancer cells based on their KRAS genetic status, utilizing both KRAS-wildtype BxPC3 and KRAS-mutant PANC1 cell lines." (PMID 38672219, 2024). "The mutations of KRAS and SMAD4, which are key genes identified in human pancreatic cancer, have also been detected on Pan02 cells." (PMID 38547077, 2024). "In this study, untargeted metabolomics was employed to uncover potential biomarkers to distinguish between KRAS-WT and KRAS-mutant pancreatic cancer cells." (PMID 38672219, 2024). "Recognizing that 95% of PC cases exhibit mutant KRAS protein and that KRAS-transformed cells have been shown to have enhanced macropinocytosis, it was anticipated that the peptide-linked arsenic compound might also target pancreatic cancers and increase the inhibition of ATO." (PMID 39518921, 2024). "Histologies of particular note included central nervous system (CNS) tumors, pancreatic tumors (all KRAS wild-type), cervical tumors and urothelial carcinomas harboring FGFR fusions or mutations." (PMID 38710951, 2024). "For the first time, there are candidate drugs that can target the main driver gene of pancreatic cancer: KRAS." (PMID 38607041, 2024). "We and others have used HPNE cells as a system to study and reconstitute the early stages of pancreatic cancer development, in particular, the activation of KRAS." (PMID 39518045, 2024).
pancreatic cancer (continued). "In this study, FTH1 expression was upregulated in most KRAS-mutant human pancreatic cancer cells and clinical pancreatic cancer tissues, contributing to PDAC progression through positive crosstalk with PYCR1 and promoting proline metabolism dysregulation." (PMID 39294443, 2024). "Early pancreatic cancer driven by mutant KRAS shows increased plasma BCAAs, with BCAT2 highly expressed in ductal cells." (PMID 39682280, 2024). "This has shown high anti-tumour potency in KRAS G12C pancreatic cancer cell line derived mouse models, with mass spectrometry analysis revealing significant decreases in MAPK pathway activation." (PMID 39372214, 2024). "In PC-3 prostate cancer cells, MYC expression was shown to be more sensitive to PPRHs, resulting in a more pronounced downregulation compared to KRAS, whereas the reverse was true in KRAS-mutant and -dependent AsPc-1 pancreatic cancer cells." (PMID 39457457, 2024). "This was restricted to CRC with microsatellite stable tumors and patients with pancreatic cancer with KRAS-mutant tumors." (PMID 38986529, 2024). "TG01 (Targovax), a peptide vaccine derived from KRAS-mutant proteins, has been tested in phase I trials of patients with multiple myeloma and resected pancreatic cancer." (PMID 39337530, 2024). "Recent research in pancreatic cancer demonstrated the potential of exosomes loaded with siRNA targeting KRAS, resulting in reduced tumor growth in models." (PMID 39200273, 2024). "The RAS protein family—KRAS, NRAS, and HRAS—consists of small GTPases, with KRAS mutations detected in 86–91% of pancreatic cancer cases." (PMID 39770538, 2024). "Therefore, based on this work, using bromodomain inhibitors to target the upregulation of HO-1 in pancreatitis, especially in patients with KRAS mutations or precursor lesions, might become a strategy to delay the initiation or progression of pancreatic cancer." (PMID 39337472, 2024). "After activation of KRAS, two parallel signalling pathways are often promoted in pancreatic cancer, namely MAPK and PIK3CA39." (PMID 39730634, 2024). "Despite identifying well-known markers like the KRAS gene, the exact regulation of pancreatic cancer progression remains elusive." (PMID 39409930, 2024). "In light of the growing research into precision medicine targeting KRAS mutant subtypes, we need to consider the applicability and future of next-generation sequencing and molecular profiling of pancreatic cancer in the clinical setting." (PMID 38610868, 2024). "Enhanced macropinocytosis in KRAS mutant cells enables uptake of exosomes despite the dense stroma of pancreatic cancers." (PMID 38576709, 2024). "This was attributed to the augmented level of cytotoxic infiltration into tumor lesions, highlighting the potential of KRAS peptide vaccines in advancing available prophylactic treatments for pancreatic cancer." (PMID 39329989, 2024). "MMP3 initially collaborates with oncogenic KRAS to drive tumorigenesis in pancreatic cancer and activate the stromal microenvironment." (PMID 38612764, 2024).
pancreatic cancer (continued). "Since current G12C inhibitors are less active in colorectal or pancreatic cancers, we also tested the combination of FTis and KRAS-G12C inhibitors on pancreatic and colorectal adenocarcinoma cells." (PMID 38278976, 2024). "In pancreatic cancer cells, KRAS is known to promote the expression of PD-L1 through reactive oxygen species (ROS)-mediated growth factor signaling." (PMID 38553450, 2024). "Combination of MEK and CDK4/6 inhibitors in KRAS-positive pancreatic cancer induced cancer cell senescence and created a physiological stress response that activated endothelial cells and sensitized tumors to PD-1 checkpoint blockade." (PMID 39286984, 2024). "KRas amplification has been shown to correlate with the presence of entotic structures in pancreatic carcinoma, suggesting a potential link between KRas signaling and the induction of entosis in human cancers." (PMID 38565900, 2024). "This study sought to silence the KRAS gene in the human pancreatic carcinoma cell line using a complex of small interfering ribonucleic acid (siRNA) and gold nanoparticles (AuNP)." (PMID 39553720, 2024). "In most pancreatic cancer patients, proto-oncogenes such as KRAS (Kirsten rat sarcoma viral oncogene homolog) are constitutionally activated, leading to uncontrolled cell proliferation, apoptotic resistance, and other oncogenic cascades." (PMID 37174108, 2023). "One study showed moderate knockdown of the KRAS gene in pancreatic cancer cells and the reduction of pancreatic tumor size with the use of EV-delivered CRISPR/Cas9 plasmids." (PMID 38138963, 2023). "We next evaluated the ability of the pan-KRASi to suppress KRAS activation and downstream signalling in a panel of 39 cell lines, originating from lung, colorectal or pancreatic cancers." (PMID 37258666, 2023). "Other advanced therapies, in this case using cell derivative nanoparticles that are under clinical evaluation (Phase I), comprise iExosomes, extracellular vesicles loaded with siRNA for the specific inhibition of KRAS G12C in pancreatic cancer (NCT03608631)." (PMID 37376135, 2023). "They found that KRAS promoted the nuclear translocation of LIN28B and that the KRAS/Lin28B axis drove the let-7i/TET3 pathway to maintain the stem-cell like phenotype of pancreatic cancer cells." (PMID 37304235, 2023). "Activation of NRF2 by 15d-PGJ2 upregulates pathways involved in glutamine metabolism, thereby promoting chemoresistance in KRAS-mutant pancreatic cancers." (PMID 37705755, 2023). "For example, peripheral blood lymphocytes with modified mTCR targeting KRAS G12D (NCT03745326, Phase I/II) and KRAS G12V (NCT03190941, Phase I/II) mutations are under clinic evaluation for rectal and pancreatic cancer, respectively." (PMID 37376135, 2023). "KRAS expression was significantly higher in Cluster2 than in Cluster1 (P < 0.001) and in pancreatic cancer samples than in normal samples (P < 0.001)." (PMID 36871072, 2023).
pancreatic cancer (continued). "30KRAS is the most common oncogene in pancreatic cancers, and several inhibitors targeted to KRAS G12C have been tested in clinical trials, including adagrasib and sotorasib, which have shown some evidence of efficacy." (PMID 38024139, 2023). "Nitidine also stabilized KRAS G4s and microscale thermophoresis analysis showed that it decreased KRAS expression in pancreatic cancer cells." (PMID 37021044, 2023). "As KRAS gene is mutated in about 85%–90% of pancreatic ductal adenocarcinoma (PDAC), it is the main driver of pancreatic cancer." (PMID 36909174, 2023). "KRAS activation promotes pancreatic cancer cell movement and infiltration through the WNT pathway, and increased WNT/β-catenin signaling enhances the stem cell-like phenotypes." (PMID 37371705, 2023). "Within this group, only four recommendations were of tier 1 clinical evidence level (1x PIK3CA/KRAS-mutated breast cancer, 1x MET-mutated kidney cancer, 1x ALK fusion-positive NSCLC, and 1x BRCA2-mutated pancreas cancer)." (PMID 38136436, 2023). "The conditional knockout of GPX4 in the KRAS-mutant mouse model was found to accelerate carcinogenesis of pancreatic cancer via the activation of inflammation in macrophages." (PMID 36670112, 2023). "We established that the eIF4A inhibitor CR-1-31B shows therapeutic activity in MYC-driven leukemia and KRAS-driven pancreatic cancer." (PMID 36900235, 2023). "SiRNA decreased KRAS mRNA levels in human pancreatic cancer cells, confirming the efficacy of iExosome uptake." (PMID 37405480, 2023). "Considering the robust inhibition of KRAS-driven pancreatic tumors reported here, we propose that directly targeting transcription should be considered as a promising treatment strategy in clinical research." (PMID 37831776, 2023). "Mutant KRAS polarizes macrophages into an M2-like protumor phenotype to promote pancreatic cancer progression." (PMID 36670112, 2023). "In this manuscript, we focused on the KRAS gene abnormalities of PDAC in describing ctDNA for the purpose of the early detection of pancreatic cancer." (PMID 36673023, 2023). "Overall, these data suggest that KRAS has considerable utility in the prognostic assessment and treatment of pancreatic cancer." (PMID 36871072, 2023). "A study of KRAS G12R-mutant pancreatic cancer patients treated with selumetinib (KOSELUGOTM; ARRY-142886, an oral MEK1/2 inhibitor) showed a median PFS of 3.0 months and a median OS of 9 months." (PMID 36675641, 2023). "In order to maintain anabolic cancer metabolism, KRAS mutant pancreatic cancer rewires several metabolic pathways, and an understanding of how this metabolic reprogramming works can help offer some therapeutic interventions." (PMID 36975494, 2023). "Another example is the phase I pan-cancer trial of KRAS G12C inhibitor sotorasib enrolled ten pancreatic cancer patients whose tumors harbored KRAS G12C alterations." (PMID 36670111, 2023). "AURKA expression is stimulated via a KRAS mutation, and high AURKA expression predicts unfavorable clinical outcomes in patients with pancreatic cancer." (PMID 37568682, 2023).